PINX1 (PIN2 (TERF1) interacting telomerase inhibitor 1 )
Diseases named in the same sentence as PINX1 in open-access papers (continued):
Sharing a sentence is not in itself a finding about the gene and the disease.
cancer (continued). "In the study by Zhou and Lu, downregulation of PinX1 expression via antisense cDNA transfection resulted in increased telomerase activity, increased telomere length and enhanced tumor malignancy in the HT1080 (telomerase-positive) cancer cell line." (PMID 24940406, 2014). "We have originally shown that whereas reducing PinX1 in human cancer cells increases their tumorigenicity, overexpression of PinX1, especially its small TID domain (telomerase-inhibitory domain) drives cancer cells into crisis and potently suppresses their ability to form tumors in mice." (PMID 22021332, 2011). "The mechanism for PinX1 gene inactivation in human cancers is not clear." (PMID 27556185, 2016). "Initially, when PinX1 was isolated, Zhou and Lu reported that the gene was located on human chromosome 8p23.1, which is a region that frequently exhibits LOH in many human cancers, and that the depletion of endogenous PinX1 increased the tumorigenicity of HT1080 cells in nude mice." (PMID 24672800, 2014). "Overexpression of PinX1 in tumor cells could inhibit telomerase activity, shorten telomeres, and suppress tumor growth, while depletion of endogenous PinX1 increased telomerase activity, elongated telomeres, and enhanced tumorigenicity in telomerase-positive HT1080 cancer cells." (PMID 24268029, 2013). "For the cancer phenotypes, the reverse genetics models were enriched in DNA repair functions (p = 2×10−5, FDR p = 0.03) (POLG/FANCI, SLX4/FANCP, XRCC1, BRCA1, FANCA, CHD1L) while the additive model showed enrichment related to chromatid segregation (p = 4×10−6, FDR p = 0.005) (KIF25, PINX1)." (PMID 24349080, 2013). "The absence of PINX1 rendered Hela cells susceptible to PARP inhibitors, a phenomenon not only confirmed in OVCAR8, OC316, and BEL7404 cancer cell lines but also validated in vivo in xenograft mouse models, suggesting PINX1 as a potential target for cancer therapy." (PMID 39174499, 2024). "Moreover, there is no genetic evidence for any involvement of PinX1 in cancer." (PMID 22021332, 2011). "However, the role of PinX1 in telomerase regulation and cancer development is not clear." (PMID 22021332, 2011).
tumor (31 papers, 2011 to 2025). "Tumor size was monitored, and the results showed that PINX1 deficient tumors are significantly more sensitive to Talazoparib treatment compared to the PINX1 proficient tumors, suggesting a promising translational possibility." (PMID 39174499, 2024). "Low PINX1 expression was also associated with lymphatic invasion (OR: 2.23, 95.0% CI: 1.35–3.70; P = 0.002) and advanced tumor-node-metastasis stage (OR: 2.43, 95.0% CI: 1.29–4.57; P = 0.006)." (PMID 30079348, 2018). "PIN2-interacting protein 1 (PinX1), a nucleolar protein associated with telomere/telomerase, is a putative tumor suppressor." (PMID 24940406, 2014). "Our findings suggested that PinX1 could be a potential tumour suppressor in NSCLC and that loss of PinX1 promoted NSCLC progression." (PMID 28815183, 2017). "Because low PinX1 expression is associated with poor prognosis, supporting PinX1 may play important roles in one or more steps of tumor metastasis." (PMID 25888829, 2015). "Depletion of PinX1 impairs rDNA transcription, compromises ribosome biogenesis and inhibits tumor cells proliferation." (PMID 40639785, 2025). "PIN2/TRF1-interacting telomerase inhibitor 1 (PinX1) functions as a telomerase inhibitor and tumor suppressor." (PMID 39634130, 2025). "PinX1 was initially thought to inhibit the activity of telomerase through its binding to telomerase, which is considered a tumor suppressor." (PMID 38431575, 2024). "In our study, silencing PinX1 in combination with radioimmunotherapy significantly reduced the proportion of Tex in tumor tissues." (PMID 38431575, 2024). "Compared to radioimmunotherapy alone, silencing PinX1 combined with radioimmunotherapy significantly increased the infiltration of CD8+ T cells in tumor tissues (p = 0.0376)." (PMID 38431575, 2024). "Our study found that silencing PinX1 combined with IR significantly increased CD8+ T cells infiltration as well as CD8+ cytotoxic T lymphocytes in tumor tissues and peripheral immune organs." (PMID 38431575, 2024). "The human PINX1 gene is a telomerase inhibitor and putative tumor suppressor gene that inhibits telomerase activity and shortens the length of telomeres to suppress tumor growth." (PMID 30079348, 2018). "It has been reported that PinX1 suppress tumor growth and depletion of endogenous PinX1 can enhance tumorigenicity." (PMID 28978030, 2017). "This variation suggests that abnormal gene regulation and/or protein functions of PinX1 in tumorigenesis are complicated and are likely to be tumor-type-specific." (PMID 28372542, 2017). "In the present study, we enrolled a total of 158 patients with NSCLC and used IHC to detect PinX1 protein expression in tumour tissues." (PMID 28815183, 2017). "It has been reported that PinX1 suppress tumor growth and depletion of endogenous PinX1 enhanced tumorigenicity." (PMID 28372542, 2017). "Because PinX1 was found to function as a tumour suppressor, we attempted to confirm our previous findings in NSCLC cells." (PMID 28815183, 2017). "In the present study, we also provided evidence of the tumour-suppressive role of PinX1 in NSCLC cells." (PMID 28815183, 2017). "PINX1 is a putative tumour suppressor and overexpression of PINX1 inhibits telomerase activity, shortens telomeres and induces crisis." (PMID 28233473, 2017). "Recent results have discovered that PinX1 is a major tumor suppressor and involved in tumorigenesis and tumor progression." (PMID 27556185, 2016). "PinX1 levels were inversely correlated with tumor multiplicity, advanced N classification, high proliferation index (Ki-67), and poor survival." (PMID 27556185, 2016). "Our data demonstrated that PinX1 expression was dramatically decreased in ccRCC tissues compared with normal renal tissues and paired adjacent non-tumor tissues." (PMID 26033551, 2015).
tumor (continued). "Our data showed that PinX1 expression was apparently decreased in ccRCC tissues compared with normal renal tissues and paired adjacent non-tumor tissues." (PMID 26033551, 2015). "In training cohort TMA slide containing 75 cases ccRCC tissues with paired adjacent non-tumor tissues, we observed that a significantly lower expression of PinX1 in tumor tissues compared with paired adjacent non-tumor tissues (P < 0.001)." (PMID 26033551, 2015). "PIN2/TRF1-interacting telomerase inhibitor 1 (PinX1) is a novel cloned gene which has been identified as a major haploinsufficient tumor suppressor essential for maintaining telomerase activity, the length of telomerase and chromosome stability." (PMID 26033551, 2015). "Due to migration and invasion ability is crucial for tumor metastasis, we examined the effects of PinX1 on migration and invasion of ccRCC cells." (PMID 26033551, 2015). "Taken together, PinX1 expression is decreased in ccRCC tissues compared with paired adjacent non-tumor tissues and normal renal tissues." (PMID 26033551, 2015). "PinX1 (PIN2/TRF1-interacting telomerase inhibitor 1) was suggested to be correlated with tumor progression." (PMID 25888829, 2015). "PinX1 is a potent telomerase inhibitor and a putative tumor suppressor, firstly found as a Pin2/TRF1-binding protein." (PMID 25888829, 2015). "We performed a univariate Cox regression analysis including PinX1 expression, age, tumor size, pT status, pN status, and TNM stage to study the effects of PinX1 on patients’ survival in ccRCC." (PMID 26033551, 2015). "Certain studies consider PinX1 to be an intrinsic telomerase/telomere inhibitor and a putative tumor suppressor, as it binds to and suppresses telomerase enzymatic activity." (PMID 24940406, 2014). "Pin2/TRF1 binding protein X1 (PinX1) has been identified as an endogenous telomerase inhibitor and a major haploinsufficient tumor suppressor gene." (PMID 24936151, 2014). "The potent tumor suppressor PinX1 was originally isolated as one of the Pin2/TRF1 interaction proteins." (PMID 24672800, 2014). "Recently, it has been reported that human PinX1 can regulate telomerase activity and suppress tumor growth both in vivo and in vitro." (PMID 24268029, 2013). "Originally, PinX1 was identified as an intrinsic telomerase inhibitor and a putative tumor suppressor because of its binding to and inhibition of telomerase." (PMID 24268029, 2013). "PinX1 levels were inversely correlated with tumor multiplicity, advanced N classification, high proliferation index (Ki-67), and poor survival (P < 0.05)." (PMID 24268029, 2013). "PinX1 has been identified as a critical component in regulating telomerase activity, and is proposed to be a putative tumor suppressor." (PMID 24268029, 2013). "PinX1 levels were inversely correlated with tumor multiplicity and advanced N classification (P < 0.05)." (PMID 24268029, 2013). "To better understand the role of PinX1 on tumor cells, we also successfully established PinX1-specific siRNA PinX1-FAM-siRNA, transfection of which significantly silenced 70% of endogenous PinX1 mRNA in NPC cells (p < 0.001)." (PMID 22316341, 2012). "Some studies have found that PinX1 can attenuate telomerase activity, inhibit growth of tumor cells and induce apoptosis." (PMID 22316341, 2012). "Pin2/TRF1 interacting protein X1 (PinX1) was recently found as a tumor suppressor and telomerase inhibitor in vivo." (PMID 22316341, 2012). "Human interacting protein X1 (PinX1) has been identified as a critical telomerase inhibitor and proposed to be a putative tumor suppressor gene." (PMID 22316341, 2012). "PinX1 has been identified as a major tumor suppressor, essential for telomerase activity and maintaining chromosome integrity." (PMID 22727333, 2012). "Tumor type specificity and posttranslational modification of PinX1 may elucidate its duality in regulating cell growth." (PMID 40639785, 2025). "Here, we report the molecular basis of the tumor suppression function of PinX1." (PMID 39634130, 2025).
tumor (continued). "Overexpression of LPTS/PinX1 could inhibit the tumor cell growth in the colorectum, breast, liver, stomach and lung, etc.." (PMID 40896430, 2025). "For NSCLC, previous studies have shown that PinX1 inhibits tumor cell proliferation." (PMID 38431575, 2024). "In the in vitro experimental part of our study (including colony formation assay and CCK-8 assay), knockdown of PinX1 also increased cell proliferation of tumor cells to a certain extent, however, when combined with RT, cell proliferation appeared significantly downregulated relative to RT alone." (PMID 38431575, 2024). "However, many studies have suggested that PinX1 positively regulates telomere maintenance and promotes genome stability in tumor cells." (PMID 38431575, 2024). "We found that silencing PinX1 combined with IR significantly inhibited tumor growth mean tumor volume on day 16 ± SEM: 930.2 ± 107.2 mm3 IR vs. 649.1 ± 44.3 mm3 shPinX1 plus IR, p = 0.0421) and dramatically improved the survival of the homograft mouse(p = 0.049)." (PMID 38431575, 2024). "The anti-tumour effects of Rec8 are caused by downregulation of cell growth-related genes (G6PD, SLC2A1, NOL3, MCM2, SNAI1, and SNAI2) and also by upregulation of both apoptosis or migration inhibitors (Gadd45G and LDHA) and tumour inhibitors (PinX1, IGFBP3, and ETS2)." (PMID 36139540, 2022). "These tumours also exhibited an increase in E-cadherin expression and a reduction in Vimentin expression in xenografts derived from PinX1 overexpression nasopharyngeal CD133+ CSCs, while the expression levels were reversed by co-inhibition of miR-200b via immunohistochemistry." (PMID 32028978, 2020). "Since its discovery as a potent telomerase inhibitor in 2001, PinX1 had been revealed to be involved in tumorigenesis and tumor progression, and evidence suggested that its functions could be tumor-type-specific." (PMID 31210926, 2019). "Second, the genetic background of PINX1 may be different in different types of tumors and the role of PinX1 in tumorigenesis complicated and may be tumor type-specific." (PMID 30079348, 2018). "The remaining copy number contains insufficient PinX1 for full inhibition of telomerase activity, which could immortalize the tumor and result in telomere lengthening." (PMID 28978030, 2017). "The telomerase/telomere interacting protein PinX1 has been suggested as a tumor suppressor." (PMID 28372542, 2017). "However, research has shown that PinX1 can have opposing molecular status in its expression patterns in several other tumor types." (PMID 28978030, 2017). "The status of PinX1 genetic alterations was correlated with prognosis and may be tumor-type specific." (PMID 28978030, 2017). "Since PinX1 is a putative tumor suppressor, we next sought to determine whether it could serve as an indicator for patient survival." (PMID 28978030, 2017). "This was done to better understand the potential role played by PinX1 in tumor development." (PMID 28978030, 2017). "Finally, HSP90AA1 was also shown to interact with PinX1, which mainly participates in stabilizing many proteins required for tumor growth." (PMID 28978030, 2017). "In addition, the pattern of PinX1 genetic expression is vastly different in various tissues and tumor types." (PMID 28978030, 2017). "These suggest that the abnormalities and/or functions of PinX1 in tumour genesis and progression are complicated and may be tumor-type-specific." (PMID 27556185, 2016). "Together all of these results indicate that PinX1 is a major tumor suppressor." (PMID 27556185, 2016). "The results of the present study support the hypothesis that combined therapy with PinX1-siRNA/DOX can successfully maintain the tumor inhibition effect with reduced side effects." (PMID 24940406, 2014). "As it has been documented that PinX1 could inhibit telomerase activity, shorten telomeres, and suppress tumor growth, we investigated whether PinX1 could influence tumor growth by regulating telomerase activity and the telomere length pathway." (PMID 24268029, 2013).
tumor (continued). "In short, the mechanisms by which PinX1 regulates telomerase/telomere in tumor cells are complex and may vary in different tumors." (PMID 22316341, 2012). "Some studies indicate that PinX1 gene can inhibit telomerase activity and induce cell apoptosis, and expression of PinX1 is negatively correlated with hTERT expression and telomerase activity in tumor cells." (PMID 22316341, 2012). "Our findings provide further support that PINX1 is a potential tumor suppressor." (PMID 22363464, 2012). "Loss of PinX1 has been found in a large variety of malignancies, however, its function in inhibiting telomerase activity of tumor cells is not well documented." (PMID 22316341, 2012). "Recent results have not only demonstrated that PinX1 is essential for maintaining telomeres at the optimal length, but also discovered that Pinx1 is a sought-after major tumor suppressor at human chromosome 8p23 that is essential for maintaining chromosome stability in vitro and in vivo." (PMID 22021332, 2011). "Moreover, almost all PinX1 heterozygous knockout mice develop a range of epithelial malignancies, with multiple tumor types in the same mice, diverse cell morphologies/grades in one tumor type among mice, or even within individual tumors." (PMID 22021332, 2011). "The recent results from my laboratory indicate that PinX1 is a major tumor suppressor at 8p23." (PMID 22021332, 2011). "Thus, almost all PinX1+/- mice spontaneously develop a range of aggressive epithelial cancers, which are unusual in mice, even after deleting many other tumor suppressors, but are known to have 8p23 LOH in humans." (PMID 22021332, 2011). "Moreover, targeting PinX1 enhanced radiotherapy-induced anti-tumor immunity." (PMID 38431575, 2024). "Therefore, low PINX1 expression promotes tumor proliferation, invasion, and migration." (PMID 30079348, 2018). "However, PinX1 protein expression differs greatly depending on the type of tumor tissue." (PMID 28978030, 2017). "Assuming a model where the 8p23 region is deleted in one copy of chromosome 8 in a tumor while the remaining copy contains insufficient PinX1 for inhibiting telomerase activity, we may expect that such a tumor will exhibit higher levels of telomerase activity than normal." (PMID 27556185, 2016). "Therefore, PinX1 is considered as telomerase inhibitor and tumor suppressor." (PMID 22316341, 2012). "This study reported the crystal structure of the TRF1TRFH-PinX1TBM complex and confirmed that PinX1 was recruited to the telomere by TRF1 predominantly via the binding to the F-X-L-X-P motif, highlighting its tumor-suppressive impact on CESC." (PMID 39634130, 2025). "Moreover, down-regulation of PinX1 combined with RT could effectively enhance anti-tumor immunity." (PMID 38431575, 2024). "Our study revealed that PINX1 maintains cellular DNA damage repair capacity independently of telomerase inhibition, introducing a new facet to PINX1’s function as a partner of PARP1, whose deletion sensitizes tumor cells to PARPi." (PMID 39174499, 2024). "Collectively, our findings identify PINX1 as a multifaceted partner of PARP1, crucial for safeguarding cells against genotoxic stress and emerging as a potential candidate for targeted tumor therapy." (PMID 39174499, 2024). "Thus, the upregulated pinX1 protein expression may contribute to inhibiting tumor growth." (PMID 35847001, 2022). "The aim of this study was to explore the mechanism through which PinX1 regulates epithelial–mesenchymal transition (EMT) and tumor metastasis in NPC and investigate its clinical significance and biological role with respect to disease progression." (PMID 32028978, 2020). "However, whether PinX1 is tumor-suppresive or promotive remains elusive." (PMID 24940406, 2014).